AGTR1 (angiotensin II receptor type 1)
Diseases named in the same sentence as AGTR1 in open-access papers (continued):
Sharing a sentence is not in itself a finding about the gene and the disease.
tumor (continued). "For example, evidence indicates that angiotensin II receptor type-1 (AT1R) blockade with an ARB, which results in unopposed angiotensin II receptor type-2 (AT2R) stimulation is capable of causing tumor angiogenesis in vivo." (PMID 35235571, 2022). "As expected, qPCR and Western blot analysis of lysates from tumor homogenates showed a decreased expression of AGTR1, increased expression of Klotho, and increased cPARP levels." (PMID 36220392, 2022). "Generally, the AngII/AGTR1 axis is considered to promote the formation of immunosuppressive microenvironments and favor tumor growth." (PMID 36505810, 2022). "We show that blocking AGTR1 in TSC2-deficient cells results in cell death in vitro and inhibition of tumor growth in vivo." (PMID 36220392, 2022). "Consistently, losartan treatment or shRNA-mediated receptor silencing significantly reduced tumor burden in an immunodeficient xenograft model, suggesting a potential role for targeting AGTR1 in LAM and other manifestations of TSC." (PMID 36220392, 2022). "After 60 days of follow-up and monitoring, mice harboring Agtr1 KD cells (AT1-shRNA) showed reduced tumor development compared with mice harboring NT-shRNA cells." (PMID 36220392, 2022). "We show that treatment of these cells with the AGTR1 inhibitor losartan or silencing of the Agtr1 gene leads to increased cell death in vitro and attenuates tumor progression in vivo." (PMID 36220392, 2022). "Renziehausen demonstrates decreased expression and increased CpG island methylation of AGTR1 within metastatic MM, compared to primary MM, implying that AGTR1 acts as a tumor suppressor gene in MM." (PMID 35574555, 2022). "Although AGTR1 expression was lower in most tumor tissues than in normal tissues, it still played a role in tumor development." (PMID 34671200, 2021). "Thereby, the inhibition of AGTR1 by antagonists such as losartan can inhibit angiogenesis, thus contributing to the suppression of tumor growth and the occurrence of metastases." (PMID 34947958, 2021). "In most tumors, ACE and AGTR1 (in the classical axis) possessed a closer correlation with non-tumor components than those members in the alternative axis and AGTR2." (PMID 34671200, 2021). "Studies have shown that the inhibition of AGTR-1 by antagonists such as losartan can suppress angiogenesis, contributing to the suppression of tumor growth and metastases." (PMID 34947958, 2021). "Ang II/AGTR1 is expressed in tumors such as the GBM, and it is associated with tumor growth and with a more aggressive tumor phenotype." (PMID 34572782, 2021). "Pancreatic (n = 42) and small-intestinal (n = 71) tumor tissues of NEN patients were analyzed for their AGTR1 mRNA levels." (PMID 33120925, 2020). "It was further shown that both cell lines retained AGTR1 expression and radioligand binding capacity during xenotransplantation and tumor growth in nude mice, as analyzed by receptor autoradiography." (PMID 33120925, 2020). "Accumulating evidence has revealed that the inhibition of AGTR1 by antagonists such as losartan and candesartan can suppress angiogenesis, thereby contributing to the suppression of tumor growth and blood metastasis." (PMID 31219799, 2019). "Next, inhibition of AGTR1 reduced tumor growth and LNM in orthotopic xenografts by bioluminescence imaging (BLI)." (PMID 31219799, 2019). "It has been shown that AGTR1 protein is expressed in benign states, such as ovarian cyst adenomas, and is involved in angiogenesis and tumor progression." (PMID 31554351, 2019). "The angiotensin II type I receptor (AGTR1) has a strong influence on tumor growth, angiogenesis, inflammation and immunity." (PMID 31219799, 2019). "Further, angiotensin II (ANGII) and AGTR1 play essential roles in tumor survival, angiogenesis, and metastasis." (PMID 30845964, 2019). "(a) Volcano plot show the proteins upregulated/ downregulated in AGTR1 high expression patients tumor tissues compared with AGTR1 low expression patients tumor tissues." (PMID 30845964, 2019).
tumor (continued). "There is evidence showing that that both ACE inhibition and AGTR1 blockade inhibit tumor angiogenesis, vascular density, tumor growth, reduced tumor volume, cell proliferation, and mitotic index and they actually reduce metastasis, too." (PMID 31554351, 2019). "Recent evidence has demonstrated that angiotensin II type I receptor (AGTR1), is involved in tumor progression and metastasis." (PMID 30845964, 2019). "In this study, we semi-quantified the levels of AGTR1 protein by immuno-histological analysis in the same section of mice tumor tissues that were injected with either Dox or PBS." (PMID 28073349, 2017). "More specifically, the tumor suppressor AGTR1 was found to be increased in 5 of the 7 tumor samples, while the tumor suppressor SPI1 was found to be increased in 4 samples." (PMID 28178311, 2017). "Experimental validation through qRT-PCR on HNSCC cell lines KB, SCC084, SCC131 and tumor sample 193T established the repressed nature of AGTR1 in HNSCC." (PMID 25186767, 2014). "These two previous instances, and the computational and experimental effort detailed here, establish AGTR1 as a potential tumor suppressor gene in HNSCC." (PMID 25186767, 2014). "Recently, a tumor suppressor function for AGTR1 has been suggested." (PMID 39941158, 2025). "KEGG and PPI analyses revealed that GNG11, LPAR1, and AGTR1, as key factors in cancer biological processes, are significantly downregulated in CC, suggesting their potential role as tumor suppressor genes, which is of profound importance in unveiling the pathogenesis of CC." (PMID 41244534, 2025). "Additionally, AGTR1 also activates M2 macrophages and neutrophils by binding with Ang II, which is crucial for tumor immune response." (PMID 39450258, 2024). "Mutational profiling results indicated that the overall tumor mutation burden and the mutation frequency of the gene TTN were higher in the low expression group of AGTR1, SUSD5, and EPHA7, while the opposite trend was observed for DNER (Supporting Informmation)." (PMID 39556695, 2024). "AGTR1 levels in tumor tissues were significantly higher than in paired paracancerous tissues." (PMID 36983741, 2023). "Moreover, between groups with unsorted CAFs, the proportion of stroma in the saline group was retained in the tumour microenvironment, but significantly decreased after treatment with ARBs, which was correlated with the proportion of AGTR1+CAFs." (PMID 36855786, 2023). "It has been proven that AGTR1 could enhance malignant phenotype of several cancer cells to promote tumour progression." (PMID 33602220, 2021). "In in vivo model, tumor volume was significantly decreased in sh-AGTR1 group than sh-NC group." (PMID 34496800, 2021). "As integral parts of the RAS, angiotensin II receptors, including angiotensin II receptor type 1 (AT1R) and angiotensin II receptor type 2 (AT2R) are implicated in tumor angiogenesis and tumor metastasis by modulating vascular wall thickness, vascular injury, and cytokine secretion." (PMID 34831211, 2021). "Study objectives were to validate AGTR1 mRNA expression and ligand binding in human NEN tissue, to investigate the biological effects of ATII in human cell models, and to evaluate the suitability of AGTR1 as a target for tumor diagnosis in a mouse xenograft model." (PMID 33120925, 2020). "To study the effect of AGTR1 on tumor growth and lymph node metastasis, we prepared two types of orthotopically implanted tumors, Balb/c-nu nude mice bearing MDA-MB-231 tumors and Balb/c mice bearing 4T1 tumors, and chose losartan, an AGTR1 antagonist, to block AGTR1." (PMID 31219799, 2019). "High expression of AGTR1 predicted a shorter survival time for Grade 1 and Grade 2 tumor patients." (PMID 30845964, 2019). "The results revealed that AMD3100 could reverse AGTR1-induced tumor growth (AGTR1: 8069±1451 vs. AMD3100: 2923±557.1) and lymph node metastasis (AGTR1: 1564±302.6 vs. AMD3100: 458.9±208.4) significantly." (PMID 31219799, 2019).
tumor (continued). "It has been extensively published that AGTR1 levels may correlate with tumor size (T stage) and distant metastasis (M stage) in some cases." (PMID 31219799, 2019). "The results were consistent with the conclusions that AGTR1 promotes tumor growth in mouse models." (PMID 31219799, 2019). "We therefore determined whether FAK/RhoA signaling pathways are activated in AGTR1-overexpressing tumor cells." (PMID 31219799, 2019). "In conclusion, we found a new role of AGTR1-mediated tumor metastasis in our study." (PMID 31219799, 2019). "AGTR1 antagonists showed suppressed tumor growth in Agtr1+ rats." (PMID 31042345, 2019). "More important, the AGTR1-CAM cells formed metastatic tumor in the stomach, liver, and spleen." (PMID 30845964, 2019). "AGTR1 protein levels in tumor tissues were also examined by ELISA in the 23 cases." (PMID 30564297, 2018). "Several mediators involved in vessel repair and vascular tone maintenance have been shown to exert stimulatory actions in tumor development and progression, including Angiotensin II, which signal through the Angiotensin II type 1 receptor (AGTR1) to trigger angiogenic actions." (PMID 29240722, 2017). "In addition, we systematically performed experiments in cultured cells and tumor xenografts to address the role and mechanism of the AGTR1 gene in the context of OS drug resistance." (PMID 28073349, 2017). "Targeting AGTR1 could significantly inhibit tumor growth via inactivation of the phosphorylation of PLC β3, which could disrupt tumor angiogenesis by reducing the VEGF production, thus inhibiting endothelial cell survival." (PMID 28439256, 2017). "Moreover, in our model, Angiotensinogen (AGT) was produced by the tumor and their receptor (AGTR1) was located in membrane from adjacent tissue." (PMID 24597571, 2014). "Besides, tumor weight was significantly reduced in sh-AGTR1 group than sh-NC group." (PMID 34496800, 2021). "While for tumor Grade 3, high expression AGTR1 did not increase death risk." (PMID 30845964, 2019). "Furthermore, the ANGII/AGTR1 transduction pathway was involved in the release of VEGF by tumor-associated macrophages, hence suggesting that host AGTR1 signaling triggers new blood vessel formation by acting on tumor microenvironment components." (PMID 29240722, 2017). "VEGFC, FGF1, INHBA, FYN, and AGTR1 promote angiogenesis, lymphangiogenesis, EMT, invasion, and tumor cell survival – constituting pro-metastatic signaling." (PMID 41006647, 2025). "Second, an immune-related gene prognostic signature were established via regression analysis, including 2 oncogenic genes (AGTR1, HTR3C) and 2 tumor suppressor genes (SERPIND1 and CD3E)." (PMID 38355782, 2024). "A549, H1975, and H1299 cell lines were derived from tumor tissues of LUAD patients with different degrees of metastasis and genders, which indicated that AGTR1 is downregulated in LUAD cells with different genetic backgrounds." (PMID 39450258, 2024). "AGTR1 is a potential biomarker for the occurrence and progression of LUAD, closely related to tumor immunity, proliferation and migration." (PMID 39450258, 2024). "We performed in vivo knockdown experiments targeting AGTR1, DNER, EPHA7, and SUSD5 in BALB/c nude mice to investigate the effects of these recurrence mRNA panel genes on GC tumor growth and metastasis." (PMID 39556695, 2024). "We then performed a xenograft assay with a mixed injection of iCCA tumour cells (HuCC‐T1 [T1], RBE) and CAFs (unsortedCAFs #1, AGTR1+CAFs #1, AGTR1−CAFs #1) in BALB/c nude mice." (PMID 36855786, 2023). "The proof of principle for AGTR1-based tumor imaging in this study may pave the way for a translation into diagnostic approaches like PET imaging and AGTR1-directed peptide receptor radioligand therapy (PRRT) for NENs employing chelator-based AGTR1 radiotracers." (PMID 33120925, 2020). "Endogenous expression of the ATII receptor AGTR1 was assessed in five NEN cell lines by RT-qPCR and compared to mRNA levels of 23 other tumor and non-tumor cell lines." (PMID 33120925, 2020).
tumor (continued). "For instance, up-regulation of ADIPOQ, AGTR1, AHNAK, ENDRA, RBP7 and SLIT2 was correlated with larger tumour size and more advanced tumour stage." (PMID 33184436, 2020). "In intrahepatic cholangiocarcinoma, activated hematopoietic stem cells (HSCs) promote tumor fibrogenesis, tumor progression and distant metastasis by mediating the epithelial-mesenchymal transition (EMT) via the Ang II/AGTR1 and CXCR4/SDF-1α axes." (PMID 31219799, 2019). "A prognostic signature based on RGs (AGTR1, CTGF, FAM3B, IL11, IL17C, PTH2R and SPAG11A) performed moderately in prognostic predictions and correlated with age, tumor stage, metastasis, number of lesions, and tumor burden." (PMID 30661062, 2019). "Collectively, AGTR1 promotes LNM by increasing the chemokine pair CXCR4/SDF-1α and tumor cell migration and invasion." (PMID 31219799, 2019). "More specifically, the AGTR1 and SPI1 genes were identified as showing copy number increases in 5 and 4 samples, respectively, whereas the expression of these tumor suppressors was downregulated in the LUSC dataset." (PMID 28178311, 2017). "mRNA expression of the candidate genes MEIS1, LDOC1, AGTR1, BAK1, TYMS and DTL were analyzed in 3 cell lines (Hep2, KB and SCC 084), 1 primary HNSCC tumor and 3 normal head and neck tissue samples." (PMID 25186767, 2014). "Further, AGTR1 is also involved in regulating immune chemokines, checkpoints and immune regulatory factors such as PECAM1, ADARB1, SPP1 and ENO1, all of them playing important roles in immune cell regulation, tumor cell proliferation and migration." (PMID 39450258, 2024). "Losartan through its activity to block angiotensin II receptor type 1 (AT1), could decrease the intra-tumoral expression of thrombospondin-1 (TNBS-1), and significantly reduce tumor collagen and hyaluronan production." (PMID 33663521, 2021). "Moreover, protein levels of AGTR1, p-MEK, p-ERK1/2 and p-STAT3 in tumor tissues were significantly down-regulated in sh-LINC00852-1 group than sh-NC group." (PMID 34496800, 2021). "Besides, the loss of LINC00852 significantly increased miR-140-3p expression, reduced AGTR1 expression and inhibited the activation of MEK/ERK/STAT3 pathway in tumor tissues from SKOV-3 xenograft mice." (PMID 34496800, 2021). "In addition, we examined the effect of the AGTR1 inhibitor losartan on CXCR4/SDF-1α expression in mouse models and tumor cells." (PMID 31219799, 2019). "AGTR1 was tested in both tumor (69 adenocarcinomas and 42 squamous cell carcinomas) and non-tumor tissue." (PMID 30917582, 2019). "However, memory B cells and plasma cells still exhibit high expression in LUAD, which suggesting that AGTR1 does not affect the activation of memory B cells and plasma cells, and their role in tumor immunity." (PMID 39450258, 2024). "The subsequent autocrine and paracrine activation of AGTR1 leads to Ca2+-intervened secretion of IGF2, ultimately promoting lung tumor development via transformation of pulmonary epithelial cells and protumoral polarization of fibroblasts and macrophages in the tumor microenvironment." (PMID 37258578, 2023). "Since the expression of AGTR1 in BRCA and AGT in LAML/LGG was related to the DNA methylation level, DNA methyltransferases might be critically involved in the DNA methylation process during tumor development and progression." (PMID 34671200, 2021).
cancer (138 papers, 2004 to 2026). A tumor composed of atypical neoplastic, often pleomorphic cells that invade other tissues. "Pre-clinical studies indicate that losartan, an angiotensin II receptor type 1 antagonist, demonstrates potential in reducing cancer-associated fibroblast (CAF) activity due to its anti-fibrotic properties." (PMID 40741380, 2025). "Either AGTR1 or FHIT methylated cases were significantly associated with HPV-positive cancers with 92.0% sensitivity (P < 0.001)." (PMID 36344942, 2022). "There is growing evidence suggesting a possible association between cancer incidence and the use of angiotensin II receptor type 1 (ATR1) blockers, that are used in the management of hypertension and cardiovascular disease." (PMID 34121975, 2021). "A data mining analysis was also performed to explore the association between AGTR1 methylation and AGTR1 gene expression, using datasets from the cBioPortal for Cancer Genomics and the Gene Expression Omnibus (GEO) database." (PMID 31538912, 2020). "The binding of angiotensin II to AGTR1 activates multiple signaling pathways, promoting cancer cell survival and proliferation." (PMID 41006647, 2025). "All of this contrasted with the observations in other cancers such as colon (for LAMP-2) or breast (for AGTR1), which presented an increase in expression levels and consequently a decrease in MMP-2 levels." (PMID 36765855, 2023). "Of note, mimicking suppression of the Ang signaling in cancer cells by inducing knockdown of the Ang receptor AGTR1 resulted in a decrease in cancer cell proliferation, explaining the effect of captopril on tumorspheroid system." (PMID 35801591, 2022). "Our results indicate that the saRNA‐enhanced MAS1 expression counteracts the Ang II/AGTR1 axis via both ligand‐dependent and ‐independent mechanisms, and is beneficial to suppress cancer development in animal models." (PMID 35712764, 2022). "Although AGTR1 has been recognized as an oncogene in several cancer types, the role in HCC remains to be fully explored." (PMID 35910032, 2022). "For example, angiotensin II receptor type 1 (AT1R) increased expression during cancer progression, while Ang II/At2R signaling exerts the opposite effect." (PMID 36304546, 2022). "With significance cutoffs of |log FC| >1 and P-value < 0.01, AGTR1 exhibited widespread low expression in pan-cancer." (PMID 34671200, 2021). "In THCA, the expression of ACE and AGTR1 was decreased in stage III/IV compared to stage I/II cancer." (PMID 34671200, 2021). "This increase in AGTR1, in the migrated cells, is in agreement with the database, indicating a correlation between AGTR1 and cancer prognosis." (PMID 30845964, 2019). "This likely results from activation of MAS1 and the inhibition of AGTR1, reducing survival and growth of the spheroids as well as cancer metastasis." (PMID 30845964, 2019). "These pathways are well-known to be activated by the ANGII/AGTR1 axis in the cardiovascular system and as well to stimulate cell proliferation, survival, and metastasis in other cancer models." (PMID 30845964, 2019). "Expression of AGTR1 has been found in several human malignant tumors, including breast, skin, and prostate, as well as gynecologic cancers." (PMID 30845964, 2019). "From the RAS pathway, possible receptors are AGTR2 and MAS1 that have opposing effects to that of AGTR1 in several cancers." (PMID 30845964, 2019). "AGTR1 was reported to be involved in diverse cancers, and is a potential therapeutic target for anticancer treatment." (PMID 28073349, 2017). "Several recent studies also support a possible role for AGTR1 in regulating cell proliferation during cancer development." (PMID 24321324, 2013). "AGTR1 also plays a key role in regulating cell growth and proliferation during the initiation and progression of cancer." (PMID 24321324, 2013). "However, miR-410 effectively targets c-MET and Angiotensin II Type 1 receptor (AGTR1) to suppress cancer." (PMID 38201476, 2023).